LHFPL3 (LHFPL tetraspan subfamily member 3)
Synonyms: LHFPL4
Tractability: Antibody: UniProt predicts a signal peptide or a membrane-spanning region; its Gene Ontology location is reachable by antibodies, with medium confidence.
Gene: Protein-coding gene on chromosome 7 (104,328,603 to 104,908,561, forward strand). Ensembl gene ENSG00000187416.
Subcellular location: Membrane
Subcellular location (Human Protein Atlas): Vesicles
Gene Ontology:
Molecular function: protein binding
Biological process: sensory perception of sound
Cellular component: plasma membrane; membrane
Genetic constraint (gnomAD): Loss-of-function variants: 5 observed, 19.21 expected, observed/expected ratio (o/e) 0.26, 90% interval 0.14 to 0.55. The upper end of that interval is the gene's LOEUF score, 0.55, which puts it in group 2 of 6, group 1 being the genes least tolerant of losing a copy. Missense variants: 249 observed, 324.26 expected, observed/expected ratio (o/e) 0.77, 90% interval 0.69 to 0.85. Synonymous variants: 133 observed, 135.24 expected, observed/expected ratio (o/e) 0.98, 90% interval 0.85 to 1.14.
Homologues: Orthologues: pig LHFPL3 (99% identical), rat LOC103692025 (98% identical), macaque LHFPL3 (98% identical), mouse Lhfpl3 (94% identical), chimpanzee LHFPL3 (94% identical), guinea pig LHFPL3 (94% identical), dog LHFPL3 (93% identical), tropical clawed frog lhfpl3 (83% identical), zebrafish lhfpl3 (73% identical), Drosophila melanogaster Tmhs (38% identical). Paralogues in human: LHFPL4 (72% identical), LHFPL5 (61% identical), LHFPL1 (22% identical), LHFPL6 (22% identical), LHFPL2 (22% identical), LHFPL7 (18% identical).
Diseases named in the same sentence as LHFPL3 in open-access papers:
LHFPL3 is named in the same sentence as 20 diseases in open-access papers, as found by Europe PMC text mining. Sharing a sentence is not in itself a finding about the gene and the disease. The quoted sentences say what the papers report.
glioma (7 papers, 2013 to 2024). A benign or malignant brain and spinal cord tumor that arises from glial cells (astrocytes, oligodendrocytes, ependymal cells). "It has been shown that the downregulation of LHFPL3 expression was associated with reduced viability, proliferation, and invasiveness of human glioma cells." (PMID 37342563, 2023). "miR-218-5p targets LHFPL3 to regulate human glioma cell proliferation, migration, and epithelial–mesenchymal transition." (PMID 39060946, 2024). "The most significantly upregulated DEG in CM was LHFPL3, which is also highly expressed in malignant glioma and can be inhibited by miRNA-218-5p thus reducing the invasiveness of glioma cells." (PMID 33046735, 2020). "The present study aimed to screen the miRNAs targeting LHFPL3 and verify the pathogenesis and development of gliomas." (PMID 30314994, 2019). "Our results showed that miR-218-5p significantly decrease the expression level of intracellular LHFPL3 by post-transcriptional regulation, and inhibited cell function in glioma." (PMID 30314994, 2019). "The study has found that LHFPL3, the expression of miR-218-5p and miR-138-5p, was downregulated, which correlates to a reduction in cell activity, proliferation, and invasive human ability glioma cells." (PMID 33431054, 2021). "Further research revealed LHFPL3 was highly expressed in glioma and a direct target of miR-218-5p." (PMID 34299149, 2021). "Therefore, miR-218-5p targeting LHFPL3 mRNA plays significant roles in preventing the invasiveness of glioma cells." (PMID 30314994, 2019). "The interaction mechanism of these two elements will elucidate the precise role of miR-218-5p and LHFPL3 in glioma progression, which will not only increase our knowledge of the pathogenesis of glioma but also enlightening in future novel therapeutic strategies." (PMID 30314994, 2019). "Namely, miR-218-5p could bind to LHFPL3 to inhibit the invasion of glioma cells." (PMID 34299149, 2021). "Moreover, targeting the interaction between miR-218-5p and LHFPL3 or restoring miR-218-5p expression may be new therapeutic methods to treat glioma patients in the future." (PMID 30314994, 2019). "Therefore, we further investigate the function of miR-218-5p by targeting LHFPL3 in glioma." (PMID 30314994, 2019). "Besides, the development of LHFPL3 as a biomarker for glioma is extremely promising." (PMID 30314994, 2019). "LHFPL3 may play a role in migration and invasion of GBM and the interaction between miRNAs and LHFPL3 mRNA may participate in the EMT of glioma cells." (PMID 30314994, 2019).
lipoma (6 papers, 2018 to 2023). A benign, usually painless, well-circumscribed lipomatous tumor composed of adipose tissue. "The LHFPL3 gene intersecting with HML_2 7q22.2 was a lipoma HMGIC fusion chaperone (LHFP) gene family member." (PMID 37342563, 2023). "MiR-218-5p can specifically bind to lipoma HMGIC fusion partner-like 3 (LHFPL3) mRNA, resulting in inhibition of EMT, decreased cellular activity, proliferation, and invasive capacity." (PMID 36354672, 2022). "By utilizing targeted RNA next-generation sequencing (NGS), fluorescence in situ hybridization (FISH), reverse transcriptase PCR (RT-PCR), and Sanger sequencing, we verified an in-frame fusion between NTRK2 and the lipoma HMGIC fusion partner-like 3 (LHFPL3)." (PMID 36531047, 2022). "Lipoma HMGIC fusion partner-like 3 (LHFPL3) is reported to be highly expressed in malignant glioma, but the relationship and mechanism between LHFPL3 and tumor is inexplicit." (PMID 30314994, 2019). "Alterations of lipoma HMGIC fusion partner (LHFPL3) were found to be more frequent in grade IV GBM, the survival rate of patients with mutations of LHFPL3 was significantly worse than the survival of patients without these alterations." (PMID 30314994, 2019). "Three genes had differential H3K4me3 and H3K27me3 peaks, Trp63 (transformation related protein 63); Wnt5a (wingless-type MMTV integration site family, member 5A); and Lhfpl3 (lipoma HMGIC fusion partner-like 3)." (PMID 30214456, 2018).
malignant glioma (3 papers, 2016 to 2020). A grade III or grade IV glioma arising from the central nervous system. "Mutations in LHFPL3 have been detected in malignant glioma patients and associated with autism risk." (PMID 26943675, 2016).
glioblastoma (2 papers, 2013 to 2018). The most malignant astrocytic tumor (WHO grade IV). "More recently, the alteration of LHFPL3 gene has been suggested to be a hallmark of primary glioblastoma." (PMID 29914565, 2018). "LHFPL3 was altered in 10 out of 30 patients (33.3%), predominantly in grade IV glioblastoma samples (36.4% vs. 25% in grade III anaplastic astrocytoma)." (PMID 24358143, 2013).
colorectal cancer (1 paper, 2021). A primary or metastatic malignant neoplasm that affects the colon or rectum. "The deletion in LHFPL3 leads to gene loss of function, which caused a worsening prognosis in colorectal cancer patients." (PMID 33431054, 2021). "DSVs in SGSM2 and LHFPL3 were relevant to colorectal cancer, whereas ADAP1, DLGAP2, ERC1, and PPP6R2 were related to gynecologic cancer." (PMID 33431054, 2021). "We found that the deletion occur in the LHFPL3 gene, which is relevant to colorectal cancer." (PMID 33431054, 2021).
exfoliation syndrome (1 paper, 2021). An autosomal dominant disorder caused by mutations in the LOXL1 gene, encoding lysyl oxidase homolog 1. "Linkage disequilibrium and epistasis analysis for this variant identified the genes LHFPL3, GALNT6, PIH1D1, ANKS1B, and METRNL as potentially involved in the etiopathogenesis of exfoliation syndrome and glaucoma, which were not previously associated with the disease." (PMID 34440405, 2021).
fibroid (1 paper, 2023). "The involvement of many proteins, such as LHFPL3, SGK1, and RhoA, shown in the protein-protein interaction network, is well established in fibroid pathogenesis." (PMID 37686244, 2023).
glaucoma (1 paper, 2021). Increased pressure in the eyeball due to obstruction of the outflow of aqueous humor. "In our study, the newly identified linked genes LHFPL3, GALNT6, PIH1D1, ANKS1B, and METRNL may be involved in the etiopathogenesis of XFS and glaucoma." (PMID 34440405, 2021).
melanoma (1 paper, 2019). A malignant, usually aggressive tumor composed of atypical, neoplastic melanocytes. "Several transcripts highly expressed specifically in melanoma overlapped LTR elements in the LHFPL3 locus, a gene whose expression was discordantly associated with survival of primary SKCM and UVM." (PMID 31537638, 2019).
stomach tumors (1 paper, 2020). "Finally, we observed overexpression of LHFPL3 in four stomach tumors harboring KMT2E-LHFPL3 fusions arising due to tandem duplications on chromosome 7q22." (PMID 33097743, 2020).
type 2 diabetes (1 paper, 2023). "In this study, we identified a novel low-frequency variant associated with type 2 diabetes, rs2891691, which lies between the ORC5 and LHFPL3 genes and showed increased accuracy of imputation and association power when using the TOPMed panel." (PMID 37148359, 2023).
cancer (3 papers, 2012 to 2022). A tumor composed of atypical neoplastic, often pleomorphic cells that invade other tissues. "However, programmed cell death 1 (Pdcd1), proprotein convertase subtilisin/kexin type 2 (Pcsk2), and LHFPL tetraspan subfamily member 3 (Lhfpl3) are known to be associated with cancer development." (PMID 35565312, 2022).
tumor (3 papers, 2019 to 2023). "LHFPL3 is involved in cell cycle control, and dysfunction of these genes may increase tumor susceptibility." (PMID 37342563, 2023).
LHFPL3 also shares sentences with these, for which no sentence is quoted: anaplastic astrocytoma (1 paper); autism (1); depression (1); gynecologic cancer (1); Obesity (1); pulmonary fibrosis (1); Uterine leiomyoma (1).